ROCR (regulator of chondrogenesis RNA)
Synonyms: formerly LINC02095
Gene: Long non-coding RNA gene on chromosome 17 (71,829,870 to 72,058,073, reverse strand). Ensembl gene ENSG00000228639.
Diseases named in the same sentence as ROCR in open-access papers:
ROCR is named in the same sentence as 4 diseases in open-access papers, as found by Europe PMC text mining. Sharing a sentence is not in itself a finding about the gene and the disease. The quoted sentences say what the papers report.
breast carcinoma (3 papers, 2022 to 2024). "ROCR has been implicated in promoting breast cancer proliferation by facilitating the expression of the oncogenic transcription factor SOX9." (PMID 38408075, 2024). "Among these, four ncRNAs (CASC8, GRIK1-AS1, LINC02188, and ROCR) exhibit diminished expression levels in breast cancer, while one lncRNA (LINC00511) displays elevated expression in breast cancer." (PMID 38408075, 2024).
tumor (1 paper, 2024). "In contrast, high expression of LINC02188 and ROCR in the Basal and Normal subtypes may increase tissue tumor infiltration and inhibit tumor development by activating T cells, plasmacytoid dendritic cells, NK cells, M1 macrophages, and other immune cell activities." (PMID 38408075, 2024). "It is therefore reasonable to hypothesize that targeting LINC02188 and ROCR in the Basal subtype and targeting LINC00511 in the Her2 and LumB subtype could reduce RNA methylation modification levels to inhibit tumor development." (PMID 38408075, 2024).
ROCR also shares sentences with these, for which no sentence is quoted: infection (1 paper); Pierre-Robin sequence (1).